TAOK2 (TAO kinase 2)
Diseases named in the same sentence as TAOK2 in open-access papers (continued):
Sharing a sentence is not in itself a finding about the gene and the disease.
chordoma (1 paper, 2022). Chordomas are rare malignant tumors arising from embryonic remnants of the notochord in axial skeleton. "Five regulators of this pathway (TAOK1, TAOK2, MOB1A/B, and LATS1) were significantly suppressed in chordoma samples and two of them are predicted targets for upregulated miRNAs (TAOK1 for miR-142, and MOB1B for miR-148a and miR-182)." (PMID 36033338, 2022).
frontotemporal lobar degeneration (1 paper, 2021). "TAOK2 was shown to be phosphorylated in AD and frontotemporal lobar degeneration brains." (PMID 33794991, 2021).
language disorder (1 paper, 2025). A category of disorders characterized by an impairment in the development of an individual's language capabilities, which is in contrast to his/her non-verbal intellect. "Proband 7, a male with borderline intellectual functioning, language disorder, and EEG abnormalities, exhibited a duplication in the 16p11.2 chromosomal region, which encompasses 30 genes, such as PRRT2, PAGR1, and TAOK2." (PMID 41009966, 2025).
lung adenocarcinoma (1 paper, 2020). A carcinoma that arises from the lung and is characterized by the presence of malignant glandular epithelial cells. "As expected, in general, TAOK2 protein was suppressed and ASAH1 protein was increased in lung adenocarcinoma in male tumor tissue and female tumor tissue." (PMID 32236130, 2020). "Results revealed that TAOK2 mRNA was down-regulated and ASAH1 mRNA was up-regulated in lung adenocarcinoma in male tumor tissue and female tumor tissue." (PMID 32236130, 2020). "To identify TAOK2 and ASAH1 expression difference in male and female tumor tissue in lung adenocarcinoma, we collected 8 pairs of tissues (tumor tissue and matched adjacent non-tumor tissue, 4 males and 4 females) by quantitative reverse transcription polymerase chain reaction (qRT-PCR)." (PMID 32236130, 2020).
lung carcinoma (1 paper, 2020). "The functional significance of ASAH1 and TAOK2 in lung cancer cells was evaluated." (PMID 32236130, 2020).
mental disorder (1 paper, 2025). A disease that has its basis in the disruption of mental process. "To assess association of the TAOK2-dysregulated genes with mental disorders, we queried significant DEGs enriched in both layer 2/3 and layer 4/5 neurons using the DisGeNET database." (PMID 41210984, 2025).
metastatic disease (1 paper, 2012).
prostate carcinoma (1 paper, 2017). A carcinoma that arises from epithelial cells of the prostate gland. "Both proteins are involved in the apoptotic process and are related to development of prostate cancer, in particular TAOK2 is critical in activation of MAPKK pathway and regulation of cell growth." (PMID 28467780, 2017).
neurodevelopmental disorder (9 papers, 2014 to 2026). A behavioral and cognitive disorder with onset during the developmental period that involves impaired or aberrant development of intellectual, motor, or social functions. "TAOK2 is a well-established risk gene for mental and neurodevelopmental disorders and has previously been studied in neuronal cell culture models as well as in constitutive knockout mice." (PMID 41210984, 2025). "TAOK2 is a serine/threonine protein kinase that has been implicated in neurodevelopmental disorders." (PMID 32236130, 2020). "Together, these data provide evidence that TAOK2 is a neurodevelopmental disorder risk gene and identify RhoA signaling as a mediator of TAOK2-dependent synaptic development." (PMID 29467497, 2019). "Clinically, TAOK2 is associated with the risk for mental and neurodevelopmental disorders." (PMID 41210984, 2025). "The participants in our study with rare variants in ALDOA, KIF22, TAOK2 and SEZ6L2 did not present with ASD or neurodevelopmental disorders." (PMID 35330733, 2022).
tumor (3 papers, 2012 to 2025). "Furthermore, both bioinformatics analysis and experimental results showed that TAOK2 was down-regulated and ASAH1 was up-regulated in male tumor tissue and female tumor tissue in LUAD." (PMID 32236130, 2020).
cancer (2 papers, 2020 to 2023). A tumor composed of atypical neoplastic, often pleomorphic cells that invade other tissues. "High-throughput screening has identified TAOK2 as a potential cancer therapeutic target and three specific small molecule compounds were found to inhibit TAOK2." (PMID 32236130, 2020).
degenerative disease (1 paper, 2016). "These include novel a-DMRs within the promoter of TAOK2 involved in the MAPK signalling pathway implicated in degenerative disease and within the promoter of an isoform of FADS2 associated with liver omega desaturation." (PMID 27663977, 2016).
genetic disease (1 paper, 2023). "Among protein-coding genes located between BP4 and 5, five genes, including TAOK2 (a pLI score of 1.00), CORO1A (0.97), MAZ (0.93), PAGR1 (0.74), and PRRT2 (0.59), have a pLI value of 0.5 or more and are associated with symptoms related to 16p11.2 deficits and are implicated in genetic disease." (PMID 38203422, 2023).
infection (1 paper, 2021). The state of being infected such as from the introduction of a foreign agent such as serum, vaccine, antigenic substance or organism. "The congruence of the lack of upregulation of ISGs and the decrease in IFN levels upon infection clearly indicates that TAOK2 is involved in the IFN production pathway and points towards the involvement of TAOK2 in IRF3-dependent cytokine expression (IFN-β and IP-10)." (PMID 34853303, 2021). "An involvement of TAOK2 and TRIM4 in MDA5 dependent responses is further supported by the lack of IFN production in TAOK2 KO cells after infection with SFV, which is an MDA5 activating virus." (PMID 34853303, 2021).
TAOK2 also shares sentences with these, for which no sentence is quoted: bipolar disorder (2 papers); Intellectual disability (2); asthma (1); cardiovascular disorder (1); Hepatic fibrosis (1); leprosy (1); liver steatosis (1); lymphoma (1); major depressive disorder (1); obsessive-compulsive disorder (1); psychiatric disorder (1); psychosis (1); self-limited familial infantile epilepsy (1); speech disorder (1); tauopathies (1).